MYC (MYC proto-oncogene, bHLH transcription factor)
Diseases named in the same sentence as MYC in open-access papers (continued):
Sharing a sentence is not in itself a finding about the gene and the disease.
cancer (continued). "The transcription factor, TCF4, which facilitates this enhancer-promoter interaction has differential binding affinity at the MYC enhancer depending on the allele of this established cancer variant rs6983267." (PMID 25658610, 2015). "The activity of this gene is normally tightly controlled, but the mutations found in human cancer cells mean that this gene is constantly switched on, and so too much MYC protein is produced." (PMID 26083714, 2015). "For example, H19 is a long non coding RNA upregulated by the proto-oncogene MYC, elevated in a wide range of cancers and associated with risk factors such as exposure to carcinogens." (PMID 26200659, 2015). "MYC oncogene, which is amplified in many human cancers including ES, encodes a transcription factor c-Myc, and affects the cellular behaviors such as cell growth, metabolism, survival and chromosomal translocations in human cancers." (PMID 26393798, 2015). "MYC-regulated lncRNAs were recently highlighted, compared to other noncoding RNAs regulated by cancer-associated transcription factors." (PMID 26003165, 2015). "Even though, c-MYC heterogeneity was observed frequently in advanced CRC, a c-MYC GCN gain in the primary cancer was often associated with poor survival." (PMID 26426996, 2015). "Three genes – PHOX2B, EXT1 and RECQL4 – appear in Vogelstein’s list of ‘cancer predisposition genes’, and one gene – MYC – appears in the list of ‘genes affected by amplifications or deletions’." (PMID 26427375, 2015). "Myc was particularly interesting, in that human MYC has been shown to be associated with an SE in a variety of cultured cancer cell lines." (PMID 26590320, 2015). "IPA TF analysis predicted activation of EZH2 and MYC, in agreement with their increased expression levels, as well as several other cancer-associated TFs." (PMID 25960784, 2015). "Increased phosphorylation of transcription factor MYC at serine 62 is a hallmark of CIP2A function in cancer cells." (PMID 25474139, 2015). "The 8q24 polymorphisms linked to EOTs and other carcinomas are situated approximately 700 kb 3′ of the MYC protooncogene, and these SNPs probably control the expression of this oncogene distally." (PMID 25173882, 2015). "Its growth inhibitory properties were observed mainly in β-catenin-activated embryonic cells and cancer cells, and were associated with decreased expression of c-MYC, cyclin D and AXIN2." (PMID 24595456, 2014). "PIK3CA mutations are tightly linked to the luminal subtypes whereas MYC amplification is common in both basal and luminal cancers." (PMID 25091696, 2014). "Several studies have implicated NME2 as a regulator of genes implicated in cancer progression such as c-MYC, PDGF-A, ITGAM and telomerase." (PMID 25249619, 2014). "These genes, which were exclusively downregulated and code for cytoplasmic, membrane and extracellular molecules, were found to be directly linked to MYC and other key cancer genes." (PMID 24416450, 2014). "Studies in the other cancer types show that the risk variants at the 8q24 are able to affect MYC promoter activity in an allele-specific manner, by influencing transcription factors binding affinity." (PMID 23752272, 2013). "MYC controls many fundamental cellular processes, and aberrant MYC expression is known to be associated with cancer." (PMID 23365639, 2013). "Amplification in chr8q24 is often considered to be associated with cancer because of the presence of the MYC (aka c-Myc) oncogene at location 8q24.21." (PMID 23468608, 2013). "Deregulation and constitutive expression of cellular MYC (c-MYC) oncogene is associated with poor prognosis of many human cancers, including a higher rate of metastasis, recurrence, and mortality." (PMID 24275945, 2013). "Reduction of viability of c-MYC-overexpressing cells following gene silencing was assessed to identify cellular factors associated with MYC-driven cancer, termed MYC-synthetic lethal genes." (PMID 24275945, 2013).
cancer (continued). "We also observed the association with cancer related gene sets, such as the MYC down-regulated gene set (miR-17 and miR-18b), as well as gene sets representing mTOR and PTEN pathways (miR-19a/b)." (PMID 24059244, 2013). "The SRSF1 gene itself is amplified in some cancer cells, and cancer-associated changes in the expression of MYC also increase SRSF1 gene expression." (PMID 23935626, 2013). "The c-MYC gene is associated with a wide variety of cancers exhibiting abnormally high levels of c-MYC expression." (PMID 24132198, 2013). "Chromosomal translocations, involving cellular MYC, a protooncogene, were discovered, shown to be a hallmark of BL, and central to the genetic basis of cancer." (PMID 24079372, 2013). "High expression of ATAD2 and MYC signaling were also associated with increased risk of cancer progression (p = 0.003 and p = 0.015, respectively), cancer-specific death (p = 0.004 and p = 0.001), and other poor-prognosis features." (PMID 23393560, 2013). "Activation of the molecular targets of pluripotency-associated genes (NANOG, OCT4, SOX2, and c-MYC) is frequently observed in poorly differentiated cancers." (PMID 24023739, 2013). "On the other hand, several functional studies have been performed on SNPs that are scattered over a 500 kb region upstream of the MYC gene, and that are associated with several cancer types." (PMID 23752272, 2013). "The ‘B SNP’ (393 kb upstream of MYC transcriptional start site) and ‘C SNP’ (−335 kb) ChIP amplicons correspond to genomic sites containing SNPs associated with cancer susceptibility." (PMID 23145106, 2012). "The SNP is situated in region 8q24 that contains no known genes but is in close proximity to FAM84B (coding for a breast cancer membrane associated protein) and the proto-oncogene MYC." (PMID 22726230, 2012). "MYC plays a crucial role in growth control, differentiation, and apoptosis, and its aberrant expression is associated with several cancers." (PMID 22383169, 2012). "Transcriptional enhancers in this region have been demonstrated to physically interact with the MYC promoter and potentially be affected by cancer-associated variants." (PMID 22848662, 2012). "The proto-oncogene v-myc myelocytomatosis viral oncogene homolog (avian) (MYC) has been determined to be the cancer-related gene closest to the region associated with cancer in GWAS." (PMID 22848662, 2012). "Increased levels of MYC protein are reported in many cancers and have, in some instances, been associated with extended half-lives for BL and pediatric lymphoblastic lymphoma (LL)." (PMID 22754359, 2012). "It is interesting to note that the gene desert region of chromosome 8 is a hot spot for cancer associated SNPs and harbors numerous enhancer elements that form long-range interactions with the MYC gene." (PMID 21533051, 2011). "MYC is involved in the development of many cancers, where its overexpression is associated with poor prognosis." (PMID 22248740, 2011). "A 1.2-Mb gene-poor region upstream of the MYC oncogene has been shown to contain at least 12 risk loci associated with different types of cancer." (PMID 21814516, 2011). "MYC activation is a common feature of many human cancers, including cancers with mutations in the RB pathway." (PMID 21573126, 2011). "It will be interesting in the future to determine in other cancer models if activation of MYC and loss of RB cooperate in HCC development by altering chromosome numbers." (PMID 21573126, 2011). "One notable exception is the locus proximal to MYC on chromosome 8q24.21 that contains multiple regions independently associated with the risk of prostate and other cancers." (PMID 21655089, 2011). "MYC oncoproteins are aberrantly expressed in a wide variety of human cancers, in most cases as a result from mutations at one or multiple levels of the MYC pathway, making them attractive targets for cancer therapy." (PMID 22132187, 2011).
cancer (continued). "Genetic mapping studies have identified multiple cancer susceptibility regions at chromosome 8q24, upstream of the MYC oncogene." (PMID 21814516, 2011). "For example, of the genes induced by both GFs and augmented by ErbB2, the proto-oncogenic transcription factor MYC has been associated with many forms of cancer often indicating poor prognosis." (PMID 20840765, 2010). "The expression of c-MYC is regulated at multiple levels and deregulation of this gene is associated with malignant transformation and cancer." (PMID 20405006, 2010). "This region is distinct from the locus proximal to MYC on 8q24 that holds alleles conferring an increased predisposition to cancer." (PMID 20844748, 2010). "Activation of MYC genes in human cancer occurs by amplification or loss of transcriptional control, which results in MYC protein overexpression." (PMID 18492263, 2008). "Among many examples are cancers such as lymphoma that are driven by an overexpressed and mutated MYC gene." (PMID 19458766, 2007). "Dysregulation of the MYC oncogene is associated with the pathogenesis of many human cancers." (PMID 40282497, 2025). "GSEA revealed suppressed MYC-associated oxidative phosphorylation pathways, suggesting a potential link between metabolic reprogramming and thrombus formation, a mechanism analogous to cancer-associated thrombosis." (PMID 41210882, 2025). "The overexpression of MYC has been linked to a poor prognosis across various cancer types." (PMID 40076599, 2025). "Out of all genomic regions, the ∼500-kb super-enhancer region on 8q24 that regulates MYC expression carries the largest burden of population-level cancer susceptibility; it contains several common alleles that increase the risk for multiple major forms of human cancer." (PMID 40180576, 2025). "Pathway analysis in tumors subjected to the two treatments suggested the downregulation of gene sets involved in cellular proliferation represented by E2F targets, G2M checkpoints, and MYC targets, whose high score is typically associated with a proliferative cancer phenotype and aggressiveness." (PMID 39962052, 2025). "MYC is the most amplified gene in cancer and is associated with poor outcomes." (PMID 41463412, 2025). "MYC is an aberrantly regulated transcription factor implicated in approximately 70% of human tumors, where it extensively modulates signaling pathways associated with cancer progression." (PMID 40732268, 2025). "In addition, inhibition of GRP78 upregulated the translational inhibitor 4E-BP1, leading to reduced expression of MYC, the most deregulated oncoprotein in cancer, and loss of viability of oncogenic MYC tumors." (PMID 40699920, 2025). "The high level of the MYC protein expression in PBL is not only related to MYC translocation, but it is caused by several different mechanisms, as the MYC gene may be activated through various cancer-promoting pathways." (PMID 40869163, 2025).
cancer (continued). "The expression of MYC, which encodes a transcription factor crucial for maintaining numerous signaling pathways and is a hallmark of active chromatin in highly proliferative cells, was similar between MSCs, cancer cells, and iPSC lines." (PMID 39621192, 2025). "In BC, STAT3 and MYC play a role in the transcription of microRNAs (miRNAs) implicated in cancer." (PMID 41186627, 2025). "This newfound understanding explains the poor prognosis associated with MYC+ cancers and offers potential therapeutic targets that could be leveraged in treatment strategies for these cancers." (PMID 40027648, 2025). "GSEA between the high- and low-SLC7A1 groups revealed significant enrichment of cancer hallmark pathways that are closely associated with cell proliferation, such as the G2M checkpoint, E2F targets, and MYC targets, which were in high accordance with the GSVA at the single-cell level." (PMID 41184266, 2025). "Hence, according to these latter results, aging appears to be associated with higher cancer incidence only in the presence of MYC." (PMID 38510176, 2024). "Hence, MYC activation has been implicated in the initiation, progression, and maintenance of most types of cancers." (PMID 39456601, 2024). "Additionally, the proto-oncogene MYC, known to be associated with cancer progression [30, -32], was also elevated in the Intestine ECM scaffold, further indicating the scaffold's potential to support enhanced intestinal gene expression." (PMID 39049484, 2024). "Moreover, several other key cancer hallmark signatures, e.g. MYC targets, E2F targets, and MTORC1 signaling were highly enriched in DR tumors." (PMID 39687207, 2024). "Our pan-cancer analysis suggests that this hallmark is important in multiple cancer types and this finding was particularly pronounced in key transcriptional regulators of proliferation, such as E2F and MYC." (PMID 39478119, 2024). "Therefore, we analyzed the expression of MYC in cohesin-mutated cancer cells after LY2090314 treatment." (PMID 38607047, 2024). "On the other hand, pVEC-ASO3 targets UBA2 mRNA, a cancer hallmark pathology in MYC-driven cancer." (PMID 38391508, 2024). "In addition, we found that high expression of the PYGB gene was associated with the G2/M cell cycle checkpoint, cancer cell proliferation, DNA damage repair, and MYC gene expression." (PMID 38483604, 2024). "MYC-induced downregulation of uPA and uPAR causes significant rearrangement of cancer cell cytoskeletal architecture (cells become rounder and compact and grow in tighter clusters), which impedes cancer cell migration by impairing their ability to invade the extracellular matrix (ECM)." (PMID 37450923, 2024). "MYC is among the most widely investigated cancer-causing genes, and is implicated in the formation, maintenance, and progression of various cancer types; approximately 70% of human cancers are associated with dysregulated MYC expression." (PMID 37450923, 2024). "Thus, the role of MYC and its association with patient mortality is dependent on the cancer lineage." (PMID 39766097, 2024). "MYC expression is frequently associated with a poor prognosis and severe cancer aggression." (PMID 39615685, 2024). "It had been widely reported that the overexpression of c-MYC was closely associated with rapid proliferation, apoptosis inhibition, promotion of angiogenesis, metabolic reprogramming, invasion, and metastasis in cancer cells." (PMID 38622518, 2024). "While MYC is most commonly associated with its function as an oncogene, there are numerous studies suggesting a role for its function in brain development, normal brain function, and multiple non-cancer brain pathologies." (PMID 38164564, 2024). "In addition, SUSD4 expression level was negatively associated with cancer proliferation, DNA repair, cellular response to hypoxia, DNA replication, MYC target genes, and G2M DNA damage checkpoint." (PMID 38579174, 2024).
cancer (continued). "Pin1 also directly interacts with and regulates the stability, nuclear localization, and transcriptional capabilities of c-myelocytomatosis (c-MYC)—a transcription factor implicated in many cancers that prominently contributes to cell proliferation, survival, and stemness." (PMID 38745861, 2024). "Indeed, evidence continues to build up linking MYC with the control of hallmark metabolic pathways in cancer cells including glycolysis, glutaminolysis, oxidative phosphorylation, and lipid metabolism." (PMID 39075086, 2024). "The MYC proto-oncogene is associated with the development of most cancers in humans." (PMID 39615685, 2024). "This area houses the well-studied oncogene MYC, implicated in approximately 20% of human cancers." (PMID 38756785, 2024). "Mutations of these ligases in a subset of human cancers delay MYC degradation." (PMID 38227944, 2024). "It is well-characterized that c-MYC is a driver of cancer in its mutated forms." (PMID 39684934, 2024). "Immunohistochemistry and western blot assays were performed to assess the expression levels of c-MYC and Ki-67 (representing the proliferation ability of cancer cells), showing that loss of STK16 significantly restrained the expression levels of c-MYC and Ki-67 in vivo." (PMID 38622518, 2024). "Furthermore, analysis of Cancer Hallmarks indicated the activation of pathway terms associated with sustaining proliferative signaling, such as MYC targets, E2F targets, G2M checkpoint, or mitotic spindle." (PMID 39024554, 2024). "MYC, the prototype member of the MYC family, is encoded by the MYC proto-oncogene located on human chromosome 8, which is among the most commonly deregulated genes during tumorigenesis occurring in over 70% of human cancers." (PMID 39031286, 2024). "The results of GSEA demonstrated that DEGs mainly enriched in several pathways associated with immune response, cancer proliferation and metastasis, such as Interferon alpha/gamma response, TNFα signaling, MYC/E2F targets, and epithelial mesenchymal transition." (PMID 39376555, 2024). "Consequently, further investigations into the underlying mechanism and biological function of the EFTUD2/c-MYC axis in cancer development are anticipated." (PMID 38163859, 2024). "Imbalanced TEADs transcriptional output leads to the signal enhancement of many oncogenes, including KRAS, BRAF, LKB1, NF2, and MYC, and subsequently facilitates tumor progression, metastasis, cancer metabolism, and immunity, and serving as the hallmark of cancer." (PMID 38607003, 2024). "Here, we sought to provide insights into this relationship using an engineered mutation-reporter mouse model we previously constructed to contain either a control B-DNA-forming sequence or a mirror-repeat H-DNA-forming sequence from the human cancer-associated c-MYC oncogene." (PMID 39595629, 2024). "This study sheds light on the mechanisms underlying MYC regulation of cancer development and may have implications for developing targeted therapies against cancer." (PMID 39615685, 2024). "Moreover, COPS5 is co-expressed with STAT3 in cancers, and MYC mediates this co-regulation associated with poor prognosis." (PMID 38974382, 2024). "Additionally, the oncogene MYC, associated with various cancer types, influences drug sensitivity in CML and aids in the survival of CML CD34+ leukemic stem cells." (PMID 38607055, 2024).